IL17A (interleukin 17A)
Diseases named in the same sentence as IL17A in open-access papers (continued):
Sharing a sentence is not in itself a finding about the gene and the disease.
skin abscess (4 papers, 2016 to 2025). "In a murine skin abscess model, the inhibition of either IL-17A or IL-22 alone resulted in significantly larger lesion size, indicating that both IL-17A and IL-22 are necessary for local control of SSTIs." (PMID 26901227, 2016). "The IL-17A/F−/− mouse develops spontaneous S. aureus skin abscesses." (PMID 40563867, 2025). "To evaluate the role of Th1 or Th17 immunity against skin abscesses, we infected naive mice with S. aureus inocula that were premixed with recombinant mouse IFN-γ, IL-17A, IL-22, or a combination of different cytokines." (PMID 30327437, 2018).
skin changes (4 papers, 2011 to 2020). "In line, no alterations in measured serum chemokine levels (IL-17A/F, IL-23, IL-18, CCL20, and CCL27) were observed either, confirming a weak relationship between serum cytokines and skin changes in all but most severely affected individuals." (PMID 33343564, 2020).
sleep disorder (4 papers, 2018 to 2024). A change from the patient's baseline sleeping pattern, in the hours slept and/or an alteration/dysfunction in the stages of sleep. "Sleep disorders promote a low-grade inflammatory status by increasing circulating proinflammatory cytokines (IL-1β, IL-6, IL-17A, TNF-α) and CRP." (PMID 30402295, 2018).
tongue squamous cell carcinoma (4 papers, 2017 to 2024). A squamous cell carcinoma that arises from the tongue. "The Cancer Genomic Atlas database correlated decreased levels of IL-17a with advanced tumor stage in OSCC, whereas another study correlated high expression of IL-17a with tumor progression in tongue squamous cell carcinoma." (PMID 36675138, 2023). "However, the exact role of IL-17A in carcinogenesis and progression of tongue squamous cell carcinoma (TSCC) remains unclear." (PMID 28035060, 2017).
Ureteral obstruction (4 papers, 2018 to 2020). Obstruction of the flow of urine through the ureter. "A recent study suggested that γδT cells, especially IL-17A producing γδT cells, accumulate following unilateral ureteral obstruction-induced renal injury." (PMID 31438987, 2019).
viral pneumonia (4 papers, 2012 to 2025). Inflammation of the lung parenchyma that is caused by a viral infection. "This study focused on evaluating the protective effects of the bifunctional protein against intestinal injury in a viral pneumonia model and comparing them with those of the anti-IL17A antibody and recombinant IL22 alone or in combination." (PMID 37189778, 2023).
acrodermatitis (3 papers, 2019 to 2026). An inflammatory skin condition affecting children. "In 2017, Baron reported a case of GT associated with acrodermatitis continua of Hallopeau with good outcome to secukinumab, a selective anti-IL-17A monoclonal antibody." (PMID 31789253, 2019). "This case report presents the novel and successful use of periungual Xeligekimab injections for managing refractory Acrodermatitis Continua of Hallopeau (ACH), representing the first documented application of this localized administration route for the IL-17A inhibitor." (PMID 41853264, 2026).
alcoholic cirrhosis (3 papers, 2020 to 2023). "Functional changes among circulating MAIT cells in patients with alcoholic cirrhosis, including increased production of IL-17A and perforin, and reduced production of TNF-α." (PMID 34321090, 2021). "LcS significantly reduced plasma monocyte chemotactic protein-1 and, on subgroup analysis, plasma interleukin-1β (alcoholic cirrhosis), interleukin-17a and macrophage inflammatory protein-1β (non-alcoholic cirrhosis), compared with placebo." (PMID 32498372, 2020). "The present study demonstrated that MAIT cells produce more IL-17A, and less TNF-α in patients with alcoholic cirrhosis." (PMID 34321090, 2021).
astrocytoma (3 papers, 2010 to 2017). "The level of IL-17A mRNA in astrocytoma is 778±27% and increases in oligodendroglioma and GBM (6658% and 4981±1344%, respectively)." (PMID 21060663, 2010).
atopic march (3 papers, 2012 to 2023). sequential manifestations of different allergic diseases such as eczema, asthma and rhinitis. "The expression of fatty-acid-binding protein 5 (FABP5) in the skin and T cells of individuals with atopic march and in murine models of atopic march showed a positive correlation with IL-17A levels in both the skin and serum." (PMID 38256282, 2023). "Here we show a novel role of S. aureus superantigen SEB in augmenting allergen ovalbumin (Ova) induced atopic march through an IL-17A dependent mechanism." (PMID 22848348, 2012). "Furthermore, when the IL-17A gene was deleted, the contribution of SEB to EC-Ova induced atopic march was diminished." (PMID 22848348, 2012).
cataract (3 papers, 2014 to 2024). Partial or complete opacity of the crystalline lens of one or both eyes that decreases visual acuity and eventually results in blindness. "We inferred that the expressions of IL-2, IL-4, IL-6, IL-10, IL-17A, and IFN-γ were the most likely to differ between inflammatory cataracts that are secondary to BD and VKH and AR cataracts." (PMID 25303043, 2014). "The expression levels of IL-2, IL-4, IL-6, IL-10, IL-17A, and IFN-γ were analyzed in the AqH, and PHA-stimulation and non-PHA-stimulated cultures of PBMCs from these three types of cataract patients." (PMID 25303043, 2014). "In the PHA-stimulated PBMC cultures, IL-2, IFN-γ, IL-6, and IL-17A were significantly increased, and the IL-6 level was significantly higher in the VKH patients than in the BD and AR cataract patients." (PMID 25303043, 2014). "So, we focused in the present study on evaluation of selected pro-inflammatory cytokines (IL-1β, IL-6, IL-8, IL-17A, and TNF-α), anti-inflammatory cytokines (IL-4, IL-10, and IL-13), and the IL-1 receptor antagonist (IL-1Ra) in the aqueous humor of FECD and/or cataract eyes." (PMID 38792359, 2024). "The expressions of interleukin-2 (IL-2), IL-4, IL-6, IL-10, IL-17A, and interferon-γ (IFN-γ) were analyzed in aqueous humor (AqH), phytohemagglutinin (PHA)-stimulated and non-PHA-stimulated cultures of peripheral blood mononuclear cells (PBMCs) from the three types of cataract patients." (PMID 25303043, 2014).
colonic adenoma (3 papers, 2015 to 2023). "The ETBF clearance prohibits colon adenoma formation and IL-17A-dependent tumorigenesis." (PMID 29474889, 2018).
differentiated thyroid carcinoma (3 papers, 2020 to 2025). Differentiated thyroid carcinoma (DTC), also known as papillary or follicular thyroid carcinoma, is a slow-growing malignancy usually presenting in adults as an asymptomatic thyroid mass. "More studies are warranted to unveil the specific role of IL-17A in tumor milieu of differentiated thyroid carcinoma." (PMID 32139737, 2020).
duodenal ulcer (3 papers, 2019 to 2024). An ulcer in the duodenal wall. "Consistent with our results, omeprazole treatment increases the frequency of CD4+ CD25+ FoxP3+ Treg cells and decreases the frequency of CD4+ IL-17A+ T cells among peripheral blood mononuclear cells (PBMCs) of patients with duodenal ulcers." (PMID 39247190, 2024). "Jafarzadeh and coworkers reported higher serum levels of IL-17A in duodenal ulcer patients compared to healthy subjects and asymptomatic H. pylori infected individuals, but our result is based on the different study setup and therefore warrants replication." (PMID 31092295, 2019). "Therefore, we examined the expression of S100A8/A9 in neutrophils from children with duodenal ulcers after stimulation of IL-17A/F." (PMID 37450409, 2023).
Erythema nodosum (3 papers, 2017 to 2023). An erythematous eruption commonly associated with drug reactions or infection and characterized by inflammatory nodules that are usually tender, multiple, and bilateral. "A study using antibodies to IL-17A reported that an important population of IL-17+ cells infiltrate the erythema nodosum (EN)-like eruption in BD skin lesions." (PMID 28753995, 2017).
fetal growth restriction (3 papers, 2020 to 2022). A fetus that does not grow beyond the 10th percentile of conventionally accepted weight for gestational age. "On the contrary, our result is corroborated with earlier observations indicating a remarkably higher titer of IL-17A in the sera of pregnant subjects complicated by fetal growth restriction (FGR) and PE as compared to healthy pregnant normotensive women." (PMID 33407460, 2021).
gram-negative bacterial infections (3 papers, 2022 to 2024). Infections caused by bacteria that show up as pink (negative) when treated by the gram-staining method. "Production of IL-23 in response to Gram-negative bacterial infection can induce production of IL-17A, but this is inconsistent with our predictions that IL-17A is a direct target of bacterial sRNAs positively associated with RSV." (PMID 38410509, 2024).
gram-positive bacterial infections (3 papers, 2011 to 2021). Infections caused by bacteria that retain the crystal violet stain (positive) when treated by the gram-staining method. "We found that patients who had the GG genotype of IL17A rs1974226 G/A SNP had increased susceptibility to Gram-positive bacterial infection in the derivation cohort and this result was replicated in the validation cohort." (PMID 22026963, 2011). "IL17A is reported to be essential for host defense against Gram-positive bacterial infection." (PMID 22026963, 2011). "This may suggest a protective role of IL-17A in early immune response in the peritoneal host defense but may also reflect the better outcomes seen following gram-positive bacterial infections, the class of organism where high levels of intraperitoneal IL-17 are typically seen." (PMID 32987705, 2020).
hepatic granuloma (3 papers, 2014 to 2022). A granuloma located in the liver. "Hepatic granuloma formation and fibrosis are upregulated by Th2 and Th17 cells, mainly secreting IL-4 and IL-17A, respectively, and downregulated by Th1 and Treg cells." (PMID 35839247, 2022).
hypoparathyroidism (3 papers, 2023 to 2025). Hypoparathyroidism is an endocrine disorder in which the parathyroid glands in the neck do not produce enough parathyroid hormone (PTH). "One patient with a heterozygous p.P368A variant had several APS-1-like components, such as hypoparathyroidism, enamel hypoplasia, and autoantibodies against IL-17A." (PMID 37235056, 2023).
ischemia reperfusion injury (3 papers, 2013 to 2025). Adverse functional, metabolic, or structural changes in ischemic tissues resulting from the restoration of blood flow to the tissue (reperfusion), including swelling; hemorrhage; necrosis; and damage from free radicals. "Interestingly, this early protection occurred also in syngeneic grafts and was accompanied by a decrease in cellular stress, as attested by lower HSP70 mRNA levels, suggesting the involvement of IL-17A in ischemia-reperfusion injury (IRI)." (PMID 23936171, 2013).
Langerhans cell histiocytosis (3 papers, 2020 to 2021). Langerhans cell histiocytosis (LCH) is a systemic disease associated with the proliferation and accumulation (usually in granulomas) of Langerhans cells in various tissues. "Plasma IL-17A detection in Langerhans Cell Histiocytosis (LCH) is currently a source of debate." (PMID 32775222, 2020).
Löfgren's syndrome (3 papers, 2010 to 2020). "The relative gene expression of IL-17A was lower in patients, statistically significant in patients with Löfgren's syndrome." (PMID 20813038, 2010).
macular edema (3 papers, 2021 to 2025). "Because of steroid dependence, secukinumab (an IL-17A inhibitor) was introduced, together with an intravitreal dexamethasone implant for refractory macular edema." (PMID 41107632, 2025). "Our results suggest that the JAK/STAT pathway is an attractive therapeutic target for IL-17A-induced macular oedema." (PMID 34356895, 2021). "The abnormal serum levels of IL-17A and intraocular IL-17A may all contribute to vascular leakage and macular oedema in patients with DMO, PDR, AMD and other retinal vascular diseases." (PMID 34356895, 2021). "Our results suggest that Tofacitinib or other JAK1 inhibitors may be re-purposed for the management of IL-17A mediated macular oedema." (PMID 34356895, 2021). "Our results suggest that IL-17A can damage the BRB through the activating the JAK1 signaling pathway, and targeting this pathway may be a novel approach to treat inflammation-induced macular oedema." (PMID 34356895, 2021).
nocardiosis (3 papers, 2022 to 2023). Nocardiosis is a local (skin, lung, brain) or disseminated (whole body) acute, subacute, or chronic bacterial infection. "Auto-Abs against cytokines have already been shown to underlie mycobacterial disease (type II IFN), mucocutaneous candidiasis (IL-17A/F), nocardiosis (GM-CSF), and staphylococcal disease (IL6)." (PMID 37196358, 2023).
non-alcoholic fatty liver (3 papers, 2020 to 2022). A benign form of fatty non-alcoholic fatty liver disease where the disease has not yet progressed to the inflammation of liver. "In addition, blocking the action of IL-17A resulted in a reduction in the intensity of inflammation in obese patients with a non-alcoholic fatty liver (NASH)." (PMID 35277002, 2022). "The frequencies of peripheral CXCR3+ IFN-γ+ T-bet+ and IL-17A+ iNKT cells were also increased in NASH patients in comparison with those in non-alcoholic fatty liver (NAFL) patients or healthy controls." (PMID 32765518, 2020).
onchocerciasis (3 papers, 2015 to 2020). Onchocerciasis is a form of filariasis, caused by the parasitic worm Onchocerca volvulus, transmitted by the black fly. "Further studies on onchocerciasis have linked an accentuated Th2/Th17 profile with individuals presenting severe forms of dermal pathology and higher IL-17A responses to a Plasmodium-derived antigen were observed in cell cultures from microfilaridermic individuals." (PMID 29931394, 2018).
optic neuritis (3 papers, 2018 to 2024). Optic neuritis is inflammation of the optic nerve, the nerve that carries the visual signal from the eye to the brain.The conditionmay cause sudden, reduced vision in the affected eye(s). "The aim of our research was to find the association of IL-17A and CYP4F2 rs1558139 gene polymorphism with optic neuritis." (PMID 29736281, 2018). "There are no studies analysing association of IL-17A concentration with ON, but we think that cytokines are very important for the development of optic neuritis." (PMID 29736281, 2018).
Papillary thyroid cancer (3 papers, 2019 to 2025). "Herein, we reported the nuclear RORγt, IL-17A, IL-23 and IL-1β in tumor cells of papillary thyroid cancer." (PMID 32139737, 2020).
pituitary adenomas (3 papers, 2018 to 2025). "The aim of the present study was to determine if the Ki-67 labelling index reflects invasiveness of pituitary adenoma and to evaluate IL-17A concentration in blood serum of pituitary adenoma patients." (PMID 29955610, 2018). "IL-17A might be a significant marker for patients with pituitary adenoma and Ki-67 labelling index in case of invasive pituitary adenomas." (PMID 29955610, 2018).
pityriasis rubra pilaris (3 papers, 2019 to 2023). A group of skin conditions that cause constant inflammation and scaling of the skin. "Anti-interleukin-17A (anti-IL-17A) therapy has been increasingly employed as a treatment option for pityriasis rubra pilaris (PRP)." (PMID 37519579, 2023).
pneumococcal meningitis (3 papers, 2012 to 2025). An acute purulent infection of the meninges and subarachnoid space caused by Streptococcus pneumoniae, most prevalent in children and adults over the age of 60. "Autoantibodies against both cytokines were associated with mortality in our pneumococcal meningitis cohort, with IL-17A showing a stronger effect in a multivariate analysis." (PMID 41161094, 2025). "For pneumococcal meningitis, we identified an association between these autoantibodies and outcome, with anti-IL-17A and anti-IFN-ω emerging as independent predictors of mortality." (PMID 41161094, 2025). "We also measured CSF IL-1β, TNF-α, IL-10 and IL-17A concentrations in 402 patients with pneumococcal meningitis (Appendix p9)." (PMID 41161094, 2025). "In pneumococcal meningitis, anti-IL-17A antibodies correlated with bacterial loads, and antibodies against IL-17A and IFN-ω were independently associated with death (adjusted odds ratios 3.06 [95% CI 1.35–6.92; p = 0.007]; 2.15 [95% CI 1.06–4.34; p = 0.033])." (PMID 41161094, 2025). "Thus, IL-17A/F seems unlikely to be involved in the chemoattractant activity of the CCL20/CCR6 axis during pneumococcal meningitis." (PMID 24699535, 2014).
pneumoconiosis (3 papers, 2015 to 2025). An occupational lung disorder caused by inhalation of dust particles. "The interleukin 17A (IL-17A) which is located on chromosome 6p and has been linked to chronic inflammation, is an important candidate gene conferring coal workers’ pneumoconiosis (CWP)." (PMID 26223249, 2015). "The association between the IL-6 -634C/G, IL-6 -174G/C, and IL-17A -832A/G gene polymorphisms and pneumoconiosis was examined in 5 studies involving 504 patients and 512 controls, 5 studies involving 660 patients and 848 controls, and 5 studies involving 1,179 patients and 1,235 controls." (PMID 40182855, 2025).
Renal dysfunction (3 papers, 2022 to 2024). "Renal dysfunction, based on serum creatinine increase, was associated with an increase in total bilirubin, direct bilirubin, GOT and with a pro-inflammatory cytokine profile including IL-2, IL-1β, IL-17A and IL-8." (PMID 36178979, 2022).
RSV bronchiolitis (3 papers, 2013 to 2024). "Our data show that increased airway IL-17A levels correlate with early neutrophil infiltration into the airways of severe RSV bronchiolitis patients." (PMID 24194936, 2013). "Using patient material, in vitro studies, and an animal model of RSV infection, we thus show that early local IL-17A production in the airways during RSV bronchiolitis facilitates neutrophil recruitment with pathologic consequences to infant lungs." (PMID 24194936, 2013). "To this end, we studied IL-17A production in newborns that were hospitalized for severe RSV bronchiolitis." (PMID 24194936, 2013). "Local IL-17A was previously detected in RSV bronchiolitis patients and is elevated during the recovery of infection in infant RSV patients." (PMID 24194936, 2013). "Therefore we measured both IL-17A and IL-8 in tracheal aspirates (TA) of infants that had been confirmed to suffer from severe RSV bronchiolitis." (PMID 24194936, 2013).
septic peritonitis (3 papers, 2014 to 2019). Septic peritonitis is an inflammatory condition of the peritoneum that occurs secondary to microbial contamination. "Septic peritonitis induced significant impairment of learning memory and exploratory activity, which was associated with a higher expression of IL-17A, IL-1β, and TNF-α in the brain homogenate." (PMID 31686986, 2019). "In the present study, we found that septic peritonitis induced a significant increase in IL-17A, IL-1β, and TNF-α in brain homogenate, and the enhanced inflammation was strongly associated with the deterioration in cognitive functions and exploratory activity." (PMID 31686986, 2019).
status epilepticus (3 papers, 2019 to 2022). Status epilepticus is defined as a continuous seizure lasting more than 30 min, or two or more seizures without full recovery of consciousness between any of them. "Moreover, at 6 weeks after pilocarpine-induced status epilepticus, the number of hilar ectopic granule cells was also markedly decreased by IL-17A deficiency without a difference in the proliferation of neural progenitors or the generation of newborn neurons in the dentate gyrus." (PMID 35875667, 2022).
tuberculous pleurisy (3 papers, 2013 to 2016). "In addition, CD4+ T cells expressing different combinations of IFN-γ, IL-2, TNF-α, IL-17A, and IL-22 have been described in tuberculous pleurisy." (PMID 23451159, 2013).